NHERF1 (NHERF family PDZ scaffold protein 1)
Diseases named in the same sentence as NHERF1 in open-access papers (continued):
Sharing a sentence is not in itself a finding about the gene and the disease.
papilloma (1 paper, 2016). A benign epithelial neoplasm that projects above the surrounding epithelial surface and consists of villous or arborescent outgrowths of fibrovascular stroma. "Two of the four pediatric atypical CP papilloma cases had scattered compact areas with loss of plasma membrane NHERF1 staining." (PMID 27229317, 2016). "This shift is not only compatible with a previously demonstrated tumor suppressor role for membrane-localized NHERF1, but can be used as diagnostic marker for distinguishing papillomas from carcinomas." (PMID 27229317, 2016). "Analysis of the NHERF1/ERM-NF2 IHC profile in CP papilloma (WHO grade I) showed similarities but also differences with normal CP." (PMID 27229317, 2016). "The continuous apical plasma membrane staining of NHERF1 was reliably detected in all 22 cases of CP papilloma and showed more robust staining than that of the inward rectifier potassium channel Kir7.1." (PMID 27229317, 2016). "Everywhere else, the morphology was papillary with an undistinguishable NHERF1 staining pattern from CP papilloma." (PMID 27229317, 2016). "In particular, NHERF1 subcellular localization is very useful in differentiating CP papilloma with compact areas from tumors of higher grades." (PMID 27229317, 2016). "Interestingly, we found that the distribution of NHERF1 changed with progression through the CP transformation spectrum: NHERF1 shifted from the apical plasma membrane in papilloma to the cytoplasm in carcinoma." (PMID 27229317, 2016). "We noted relatively decreased apical plasma membrane staining of NHERF1 and moesin in papilloma." (PMID 27229317, 2016). "Importantly, compact areas with similar morphology from CP papilloma and carcinoma could be readily distinguished by NHERF1 IHC." (PMID 27229317, 2016). "NHERF1 IHC also shows a characteristic pattern in PTPR, with mixed microlumen and focal apical plasma membrane staining, and distinguishes this tumor from CP papilloma." (PMID 27229317, 2016).
prostate tumors (1 paper, 2021). "The present data collectively show that NHERF-1 is downregulated by MINDIN in primary prostate tumors causing an increase in tumor cell proliferation and migration." (PMID 33498862, 2021). "Our in vivo and in vitro results show that NHERF-1 downregulation is induced by MINDIN in prostate tumor cells." (PMID 33498862, 2021). "Our data show a decrease in NHERF-1 immunolabeling in primary human prostate tumors compared to control samples." (PMID 33498862, 2021). "We next evaluated the actions of NHERF-1 on cellular processes that have previously been described to be triggered by MINDIN in prostate tumor cells and are involved in tumor progression, such as cell migration, proliferation and osteomimicry features." (PMID 33498862, 2021). "Furthermore, NHERF-1 was found both at the apical plasma membrane and cytoplasm in control prostate samples, whereas the scarce presence of NHERF-1 showed in prostate tumors was predominantly cytoplasmic." (PMID 33498862, 2021). "Furthermore, we observed that MINDIN silencing increased the expression of NHERF-1 in primary prostate tumors." (PMID 33498862, 2021). "Therefore, it might be possible that NHERF-1 mediates, at least in part, MINDIN-dependent action on prostate tumor cell proliferation via NF-kappa β activation." (PMID 33498862, 2021).
Psammomatous Meningioma (1 paper, 2018). A WHO grade I meningioma characterized by the presence of psammoma bodies that predominate over the meningeal cells. "The meningothelial variant showed weak cytoplasmic NHERF1 staining, similar to other common variants, such as fibrous, transitional and psammomatous meningioma." (PMID 29983887, 2018).
Secretory Meningioma (1 paper, 2018). A WHO grade I meningioma characterized by the presence of epithelial differentiation and numerous intracellular PAS positive bodies that are rich in glycogen. "As in secretory meningioma, moesin but not NF2 appeared to be expressed with NHERF1 in the dot-like structures." (PMID 29983887, 2018).
subependymoma (1 paper, 2015). Subependymoma is a rare and slow growing type of ependymoma, often presenting in middle-aged adults, found more commonly in men than in women, usually located in the fourth and lateral ventricles and manifesting with variable symptoms including headache, nausea, and loss of balance. "WHO grade I subependymomas showed sparse diffuse NHERF1 microlumen labeling in 100% of the cases, with a density of 1 microlumen/4 nuclei." (PMID 25775275, 2015).
viral infection (1 paper, 2019). "While the functions of NHERF1 are varied due to its role as a scaffold, multiple studies indicate it regulates cell growth and differentiation, two key cellular functions that papillomaviruses disrupt in the process of viral infection." (PMID 31002735, 2019).
tumor (56 papers, 2006 to 2025). "NHERF1/EBP50 is a master regulator of oncogenic signal networks that is involved in cell proliferation and tumor formation by assembling cancer-associated proteins, including those belonging to the PI3K/Akt and Wnt/β-catenin pathways." (PMID 37305043, 2023). "A similar behavior has been also observed in advanced colorectal cancer (CRC), where overexpression of nuclear NHERF1 in association with hypoxic microenvironment and tumor invasive phenotype has been reported." (PMID 29716631, 2018). "In tumor tissues, β-catenin was predominantly associated with NHERF1 in a dynamic context, while interestingly in liver metastases, we noted an increase of its oncogenic function through RASSF1A inactivation." (PMID 27765918, 2016). "Cytoplasmic NHERF1 was higher in C than in NM and overexpressing tumours resulted associated with nodal and distant metastases, poor grade and LVI." (PMID 23991686, 2013). "PAR-2 correlated with cytoplasmic NHERF1 and the PAR-2(+)/cytoplasmic NHERF1(+) expression immunophenotype identified tumours associated with unfavourable prognosis and aggressive clinical parameters." (PMID 23991686, 2013). "In our series, 13% of tumors showed NHERF1 still localized in the plasma membrane, and were positively associated with favorable prognosis parameters, such as low tumor grade, positive PR status, and low proliferative activity." (PMID 22439624, 2012). "Intriguingly, it was emerged that familial tumors with grade 2 were prevalently associated to the PVI+/membranous NHERF1-expression subset, confirming one more time the prognostic relevance of this tumor immunophenotype." (PMID 22439624, 2012). "Others have demonstrated that the hypoxia associated with tumor necrosis can increase EBP50 (NHERF1), which increases Na+/H+ activity, in turn decreasing local pH and promoting tumor dissemination." (PMID 21672215, 2011). "Haploinsuficient NHERF1 tumor suppressor activity would also explain the relatively low frequency of intragenic mutations, although the possibility that other NHERF1 pathway components are genetically altered cannot be ruled out." (PMID 18190691, 2008). "The finding that the phosphorylation status of NHERF1 oscillated during the cell cycle implicated possible link of NHERF1 to tumor-related response." (PMID 18190691, 2008). "Such loss is infrequent, however, in other tumour types, suggesting that NHERF1 is specifically targeted during mammary tumourigenesis." (PMID 17078868, 2006). "NHERF1 gene overexpression is associated with: i) the development of acute inflammatory response, ii) a protective role against acute injury and iii) the promotion of metastatic tumor behavior." (PMID 35223518, 2022). "Moreover, the down-regulation of NHERF1 was significantly associated with both Wnt signaling and cell proliferation thus suggesting a potential tumor-suppressive role." (PMID 35223518, 2022). "Nuclear NHERF1 expression was associated with small tumor size and positive hormonal status." (PMID 29029467, 2017). "The administration of anti-VEGF/VEGFR drugs could cause the downregulation of NHERF1 expression in cancer cells, which could contribute to the progression of tumor and the acquired resistance to drugs." (PMID 27999191, 2017). "At the same time, the shift of β-catenin and NHERF1 from the membrane to the cytoplasm, reported in tumor tissues, could be explained as it is linked to the oncogenic condition in tumor progression." (PMID 27765918, 2016). "Speculatively, alterations of these factors in mammary gland may cause an imbalance of NHERF1 level that could lead to neoplasia." (PMID 17078868, 2006). "However, the NHERF1-Y24S mutation lost the tumor-suppressor effects observed in NHERF1-wt." (PMID 27097111, 2016). "For instance, the overexpression of NHERF1 seems to be required to drive the early phases of cancer onset in different tumor types." (PMID 35223518, 2022).
tumor (continued). "Normal-appearing glandular structures were scattered within the tumor, and were lined by a monolayer of epithelial polarized cells labeled by NHERF1, a polarity marker structuring microvilli at the apical plasma membrane of epithelial cells." (PMID 35978432, 2022). "Regarding NHERF-1, this scaffolding protein has been involved in both tumor progression and inhibition in different types of cancer." (PMID 33498862, 2021). "Although these features are indicative of a tumor suppressor function, NHERF-1 has been involved in both tumor progression and inhibition." (PMID 33498862, 2021). "Our assessment of NHERF-1 localization in subcellular compartments shows that NHERF-1 is present at the apical cell membrane and cytoplasmic compartments in control samples whereas tumor samples show decreased levels and cytoplasmic expression of NHERF-1." (PMID 33498862, 2021). "Na+/H+ exchanger regulatory factor (NHERF-1) is a scaffold protein that has been involved both in tumor regulation and osteogenesis." (PMID 33498862, 2021). "The presence of NHERF-1 in the cell nuclei of tumor cells has been observed in several cancer types." (PMID 33498862, 2021). "In its physiological localization at the plasma membrane, NHERF1 has been shown to act as a tumor growth and invasion suppressor in vitro and in vivo." (PMID 31963394, 2020). "In a few reports, it was also implied that NHERF1 lost its tumor suppressive function once mislocated from the cytoplasm into the nucleus, or even worse acted as a pro-oncogene product." (PMID 32164629, 2020). "The nuclear NHERF1 played a role on promoting tumor progression through the interaction with YAP and increased YAP translocation into the nucleus for transcription activation." (PMID 32164629, 2020). "The reduction in NHERF1 expression in cancer cells treated with crizotinib is likely to suggest acceleration of tumor progression, as well as the resistance to drugs." (PMID 32164629, 2020). "We scored the extent of NHERF1 microlumen formation in the tumors and found significant correlation between the extent of microlumen labeling and tumor location (p = 0.0001)." (PMID 31963394, 2020). "In fact, NHERF1 has also been suggested to connect with tumor sensitivity to drugs targeting EGFR, MRP4 or MRP2." (PMID 32164629, 2020). "Nevertheless, recently we demonstrated a pivotal role of NHERF1 in the orchestrate tumor microenvironment signaling pathways, with a strictly association with angiogenic factors and epithelial-mesenchymal transition proteins." (PMID 31540486, 2019). "APCMin/+ mice bred as either heterozygote or knockout for NHERF1 experience considerably shorter survival than their NHERF1-expressing counterparts due to increased tumor burden, demonstrating a tumor suppressor phenotype for NHERF1." (PMID 31002735, 2019). "Recent data earmark NHERF1 as a tumor suppressor upstream of Wnt/β-catenin-driven intestinal tumorigenesis in vivo." (PMID 29551770, 2018). "From this point of view, it is very interesting to consider the mimicry involving NHERF1+ tumor cells in neo-microvessels formation, and this opens a new stimulating scenario for further NHERF1 studies." (PMID 29716631, 2018). "NHERF1 involvement in neovascularization phenomena has already been reported, but this is the first evidence of a possible direct participation of tumor cells NHERF1 positive to new-vessels formation." (PMID 29716631, 2018). "Further, immunofluorescence revealed an involvement of tumor cells with NHERF1 positive staining in neo-vascular formation, suggesting a “mosaic” structure development of these neo-vessels." (PMID 29716631, 2018). "NHERF1 displays a tumor suppressor role when it is localized at the plasma membrane, while it acts as a tumor promoter when it is localized in the cytoplasm or in the nucleus." (PMID 29152120, 2017). "In the same Group 1, we observed a lower expression of membranous β-catenin and membranous NHERF1 in paired liver metastasis than in the tumor samples." (PMID 29152120, 2017).
tumor (continued). "NHERF1 expression was detected in the apical membrane, cytoplasm, and nucleus of 281/308 (91.2%) tumor cases." (PMID 29029467, 2017). "Regarding the tumor compartment, it was found that cytoplasmic β-catenin expression was positively correlated to membranous (r = 0.3002, p = 0.0323) and nuclear NHERF1 (r = 0.293, p = 0.0368)." (PMID 27765918, 2016). "A tumor suppressor role has also been proposed for NHERF1, when localized at the membrane, through effects of the membrane-localized adaptor on its PTEN and β-catenin ligands." (PMID 27229317, 2016). "Nuclear NHERF1 protein expression was higher in cancer cells than in adjacent non-tumor mammary epithelial cells." (PMID 27097111, 2016). "The location of the tumor, papillary architecture, and presence of microlumens by NHERF1 IHC offer the best clues to the diagnosis of this entity." (PMID 27229317, 2016). "Since NHERF1 and ERM-NF2 proteins show polarized expression in choroid plexus (CP) cells, we tested their diagnostic utility in CP neoplasms." (PMID 27229317, 2016). "Clinical studies show an association between NHERF1 overexpression and the malignant progression of cancer; however, contradictory results were reported in many in vitro studies indicating a tumor suppressor role of NHERF1." (PMID 27097111, 2016). "Considering this aspect and in agreement with our previous results, in this study we observed membranous NHERF1 localization higher both in tumor-adjacent normal tissue and in tumors than in paired liver metastases." (PMID 27765918, 2016). "NHERF1 has been shown to exert a tumor suppressor function when localized at the plasma membrane, and perhaps loss of plasma membrane localization permits oncogenic progression in CP tumors." (PMID 27229317, 2016). "Cytoplasmic or nuclear NHERF1 (cNHERF1 and nNHERF1, respectively) expression was evaluated in 84.2% (80/95) of tumor samples." (PMID 26312763, 2015). "NHERF1 behaves as a tumor and epithelial-to-mesenchymal transition suppressor in cultured cells, through its effects on PTEN and β-catenin, and is required for gland morphogenesis with lumen formation in three-dimensional polarized epithelium." (PMID 25775275, 2015). "In this study, we aimed to determine the distribution of tryptase(+) MCs and PAR-2 and to examine the relationship between PAR-2 and NHERF1, investigating their reputed usefulness as tumour markers." (PMID 23991686, 2013). "Given the fundamental association between these two tumour markers, we examined the potential prognostic role of the PAR-2/NHERF1 immunophenotypes." (PMID 23991686, 2013). "We therefore examined the potential prognostic role of PAR-2/NHERF1 immunophenotypes on the basis of the significant correlation between these two tumour markers." (PMID 23991686, 2013). "In this context, NHERF1 acts as a potential interacting partner of VEGFR1, a marker correlated with high metastasis risk and relapse, probably promoting invasion of tumor cells through autocrine and paracrine mechanisms." (PMID 22439624, 2012). "NHERF1/EBP50 gene mutations were identified in cancer cells, in addition knockdown of EBP50 increased cellular proliferation and migration of cancer cell lines suggesting that EBP50 acts as a tumor suppressor." (PMID 22523604, 2012). "The present study verifies that NHERF1 has tumor suppressor activity, providing evidence to suggest that its function relies on an intact PTEN pathway." (PMID 18190691, 2008). "A possible activity of NHERF1 in counteracting the Akt pro-oncogenic pathway raises an attractive mechanism that explains NHERF1 tumor suppressor activity in mammary glands." (PMID 18190691, 2008). "Collectively, our present study indicates that NHERF1 binds to PTEN to downregulate the PI3K-Akt pathway to elicit tumor suppressor activity." (PMID 18190691, 2008).